LUC7L2 (LUC7 like 2, pre-mRNA splicing factor)
Description:
May bind to RNA via its Arg/Ser-rich domain.
Synonyms: CGI-59; CGI-74; H_NH0792N18.3; FLJ10657; LUC7B2; hLuc7B2
Tractability: PROTAC: ubiquitination databases record sites on it; its protein half-life has been measured.
Gene: Protein-coding gene on chromosome 7 (139,340,359 to 139,425,496, forward strand). Ensembl gene ENSG00000146963.
Subcellular location: Nucleus speckle; Nucleus, nucleoplasm
Subcellular location (Human Protein Atlas): Nucleoplasm
Gene Ontology:
Molecular function: enzyme binding; protein binding; RNA binding; mRNA binding
Biological process: mRNA splice site recognition
Cellular component: nuclear speck; U1 snRNP; U2-type prespliceosome; nucleoplasm
Genetic constraint (gnomAD): Loss-of-function variants: 25 observed, 50.11 expected, observed/expected ratio (o/e) 0.5, 90% interval 0.36 to 0.7. The upper end of that interval is the gene's LOEUF score, 0.7, which puts it in group 2 of 6, group 1 being the genes least tolerant of losing a copy. Missense variants: 328 observed, 496.97 expected, observed/expected ratio (o/e) 0.66, 90% interval 0.6 to 0.72. Synonymous variants: 144 observed, 163.31 expected, observed/expected ratio (o/e) 0.88, 90% interval 0.77 to 1.01.
Homologues: Orthologues: guinea pig LUC7L2 (99% identical), mouse Luc7l2 (99% identical), pig LUC7L2 (99% identical), macaque LUC7L2 (97% identical), chimpanzee LUC7L2 (95% identical), dog LUC7L2 (94% identical), rabbit LUC7L2 (92% identical), rat Luc7l2 (92% identical), tropical clawed frog luc7l2 (80% identical), zebrafish zgc:158803 (67% identical), Drosophila melanogaster CG7564 (53% identical), Caenorhabditis elegans luc-7L (30% identical). Paralogues in human: LUC7L (71% identical), LUC7L3 (37% identical).
Diseases named in the same sentence as LUC7L2 in open-access papers:
LUC7L2 is named in the same sentence as 25 diseases in open-access papers, as found by Europe PMC text mining. Sharing a sentence is not in itself a finding about the gene and the disease. The quoted sentences say what the papers report.
glioblastoma (4 papers, 2024 to 2025). The most malignant astrocytic tumor (WHO grade IV). "Histone H3K9 lactylation was shown to confer temozolomide resistance in glioblastoma through LUC7L2-mediated retention of the MLH1 intron." (PMID 41035644, 2025). "For example, elevated H3K9la promoted the transcription of interleukin-11, resulting in CD8+ T cell dysfunction in head and neck squamous cell carcinoma, as well as enhanced LUC7L2 transcription, conferring temozolomide resistance in glioblastoma." (PMID 40784455, 2025). "Induction of glioblastoma (GBM) resistance to temozolomide (TMZ) through the promotion of LUC7L2 transcription, inhibition of MLH1 splicing, and reduction of mismatch repair (MMR) system activity." (PMID 41179284, 2025).
myelodysplastic syndrome (4 papers, 2016 to 2024). A clonal hematopoietic disorder characterized by dysplasia and ineffective hematopoiesis in one or more of the hematopoietic cell lines. "Recent researches have shown that the deficiency of LUC7L2 results in aberrant splicing of transcripts which probably contribute to the pathogenesis of myelodysplastic syndromes (MDS)." (PMID 34907164, 2021). "Mutations in LUC7L2, PRPF8,SF3B1, SRSF2, U2AF1, and ZRSR2 genes occur at various frequencies ranging between 40% and 85% in different subtypes of myelodysplastic syndrome (MDS) and 5% and 10% of acute myeloid leukemia (AML) and myeloproliferative neoplasms (MPNs)." (PMID 31766606, 2019).
acute myeloid leukemia (3 papers, 2019 to 2022). Acute myeloid leukemia (AML) is a group of neoplasms arising from precursor cells committed to the myeloid cell-line differentiation. "Depletion of LUC7L2 loci is more prevalent in high-risk MDS than in low-risk MDS, and low LUC7L2 expression correlates with significantly shorter survival in primary acute myeloid leukemia (pAML) patients." (PMID 34907164, 2021). "In 2013, the association between LUC7L2 mutation (giving rise to the truncated LUC7L2 R279X variant) and the evolution from MDS to acute myeloid leukemia (AML) was reported." (PMID 35885562, 2022).
head and neck squamous cell carcinoma (3 papers, 2021 to 2025). A squamous cell carcinoma that arises from any of the following anatomic sites: lip and oral cavity, nasal cavity, paranasal sinuses, pharynx, larynx, and salivary glands. "For example, stimulator of interferon genes (STING) was identified as the sole statistically significant target in a screen conducted in head and neck squamous cell carcinoma, while LUC7L2 was found to drive radioresistance in nasopharyngeal cancer by up-regulating autophagy." (PMID 40073141, 2025). "Firstly, we inspected the correlation of the expression of LUC7L2 and SQSTM1 in Head and neck squamous cell carcinomas (HNSCC) using The Cancer Genome Atlas (TCGA) database (n = 502)." (PMID 34907164, 2021).
nasopharyngeal carcinoma (3 papers, 2021 to 2025). A carcinoma arising from the nasopharyngeal epithelium. "Downregulation of LUC7L2 in radioresistant nasopharyngeal carcinoma cells leads to suppression of sequestosome 1 (SQSTM1 or p62), expression and elevation of autophagy level." (PMID 39075259, 2024). "Moreover, knockdown of LUC7L2 combined with autophagy inhibitor, chloroquine (CQ), increased cell death in radioresistant nasopharyngeal carcinoma." (PMID 39075259, 2024).
chordoma (2 papers, 2023 to 2024). Chordomas are rare malignant tumors arising from embryonic remnants of the notochord in axial skeleton. "Genes were selected to represent both those functionally connected to other chordoma dependency genes (PTPN11, FANCM, ADAR, PRKRA, SOX9, SRRM2, SLC2A1, and SLC7A5), as well as those with putatively unique effects (LUC7L2 and CDK6)." (PMID 37024492, 2023). "Several candidate genes, including OTUD5, CDK6, LUC7L2, IER3IP1, and HEATR3, were not linked to other chordoma dependency genes following either of these two approaches." (PMID 37024492, 2023).
viral infection (2 papers, 2021 to 2022). "In this study, we found that LUC7L2 was induced following viral infection and promoted MITA/STING intron retention, leading to decreased expression of MITA/STING and attenuation of innate immune responses to DNA virus." (PMID 34155193, 2021). "Since knockout of LUC7L2 increases MITA level in the absence of viral infection, our results suggest that LUC7L2 regulates MITA level constitutively in the cell." (PMID 34155193, 2021).
autoimmune disease (1 paper, 2021). A disorder resulting from loss of function or tissue destruction of an organ or multiple organs, arising from humoral or cellular immune responses of the individual to their own tissue constituents. "It would be interesting to investigate potential roles of LUC7L2 in regulation of carcinogenesis, cancer immunotherapy, and autoimmune diseases." (PMID 34155193, 2021).
COVID-19 (1 paper, 2022). A disease caused by infection with severe acute respiratory syndrome coronavirus 2. "Of note, we observed numerous DTU genes involved in RNA splicing, with 10 genes (e.g. HNRNPC, SNRPD3, QKI, and LUC7L2) increased major transcript usage and 18 genes (e.g. SNRNP48, NCBP1, CELF2, RALY, and PABPC1) decreased major transcript usage in the COVID-19 patients." (PMID 35421082, 2022). "Furthermore, we observed that the major transcript of multiple genes switched to a different transcript (isoform switching) between COVID-19 patients and controls, such as IL2, IL34, SERPINE2, NCBP1, HRAS, PRPF6, NCBP2, and LUC7L2." (PMID 35421082, 2022).
encephalitis (1 paper, 2021). An acute inflammatory process affecting the brain parenchyma. "Given that HSV-1 is a neurotropic virus that causes sporadic encephalitis, we intranasally infected Luc7l2+/+ and Luc7l2−/− mice with HSV-1 and examined HSV-1 loads in the brains." (PMID 34155193, 2021).
ovarian tumor (1 paper, 2024). "The role of genes encoding such proteins, LUC7L2, MRPL46, MRPL14, PARP4, STRAP, and PAPOLA, in ovarian tumor development has already been investigated in the literature." (PMID 39456618, 2024).
cancer (4 papers, 2021 to 2024). A tumor composed of atypical neoplastic, often pleomorphic cells that invade other tissues. "It was possible that cells with high expression of LUC7L2 tended to overcome the radiotherapy, leading to more cancer cell survival." (PMID 34907164, 2021).
tumor (2 papers, 2023 to 2024). "In in vivo experiments, stiripentol markedly inhibited the expression of H3K9la and LUC7L2, but promoted that of MLH1, and combination therapy with stiripentol and TMZ dramatically decreased tumor growth and substantially prolonged the survival of mice." (PMID 38477507, 2024).
brain disease (1 paper, 2015). "Moreover, 10 genes (ATP1A1, ATP6V1D, C16orf45, CROCC, KLC1, LUC7L2, PIAS2, PRKAR1B, RBFOX1, and RPL19) interacts with at least one brain disease-associated gene." (PMID 26043779, 2015).
infection (1 paper, 2021). The state of being infected such as from the introduction of a foreign agent such as serum, vaccine, antigenic substance or organism. "Knockout of LUC7L2 significantly potentiated transcription of downstream antiviral genes such as IFNB1 and ISG56 induced by infection of the DNA virus HSV-1 but not the RNA virus Sendai virus (SeV)." (PMID 34155193, 2021).
LUC7L2 also shares sentences with these, for which no sentence is quoted: hematological cancers (1 paper); Hypertension (1); leukemia (1); liver cancer (1); lung adenocarcinoma (1); malignant mesothelioma (1); myeloid neoplasm (1); myeloproliferative neoplasm (1); ovarian carcinoma (1); pancreatic ductal adenocarcinoma (1).